LINC00511 (long independently transcribed non-coding RNA 511)
Diseases named in the same sentence as LINC00511 in open-access papers (continued):
Sharing a sentence is not in itself a finding about the gene and the disease.
tumor (continued). "A particularly promising finding in the noncoding human genome comprised recurrent, focal copy number deletions (chromosome 17: 72429007–72450223) in MSI tumours, involving the lincRNA LINC00673 (also known as LINC00511), a transcript that interacts with the CRC driver genes EZH2 and PTPN11." (PMID 39112709, 2024). "LINC00511 can induce stemness in cancers and facilitate tumor progression and metastasis." (PMID 37124625, 2023). "In the Basal subtype, high expression of LINC02188 and LINC00511 may increase immune infiltration of tumor tissue by activating various immune cells, thereby inhibiting tumor development." (PMID 37758759, 2023). "The oncogene LINC00511 (LINC00511) influenced tumor growth, migration, and poor outcome." (PMID 35790898, 2022). "There are numerous previous reports in the literature demonstrating that Linc00511 could regulate tumor cell proliferation, apoptosis, migration, and invasion." (PMID 35842617, 2022). "Expression of LINC00511, which promotes tumor metastasis and proliferation, can be downregulated by EGCG, and miR-29b, as a downstream target of LINC00511, can be inhibited by this lncRNA, thus increasing expression of carcinogenesis-related KDM2A (a kind of KDM)." (PMID 34235089, 2021). "We found that cell apoptosis increased after LINC00511 knockdown, which may be one of the mechanisms of sh-LINC00511 inhibiting tumor growth." (PMID 33898446, 2021). "Finally, we performed stable LINC00511 expression experiments in vivo, and the results confirmed that LINC00511 overexpression markedly induced tumor cell growth." (PMID 34088337, 2021). "We analysed tumor cell invadopodia and further showed that LINC00511 induced invadopodia formation." (PMID 34088337, 2021). "As is known to us, high expression of LINC00511 could significantly influence tumor size mentioned before." (PMID 31897240, 2020). "Nevertheless, how LINC00511 regulates these tumor-associated signaling pathways and proteins has not been unveiled, which deserves further explorations." (PMID 32713253, 2020). "Additionally, LINC00511 appeared to be correlated with age, clinical stage, tumor size, and lymph node metastasis." (PMID 32733536, 2020). "Generally, LINC00511 expression is most closely to tumor size and it may influence the tumor proliferation." (PMID 31897240, 2020). "Overall, the results from our study demonstrated that LINC00511 could function as a tumor promoter by targeting miR-625-5p NFIX axis, suggesting LINC00511 could be considered as a target for GC treatment." (PMID 31889903, 2019). "The knockdown of LINC00511 repressed the tumour growth in vivo." (PMID 30973678, 2019). "We determined that LINC00511 promotes tumour growth and inhibits apoptosis." (PMID 31395854, 2019). "Finally, xenograft model in mice assay showed that LINC00511 silencing inhibited the tumor growth (volume and weight) in vivo." (PMID 30482236, 2018). "Linc00511 expression levels in tumour tissues were categorized as low or high depending on whether linc00511 expression was up‐ or down‐regulated compared with the corresponding adjacent non‐tumoral tissue samples." (PMID 28984028, 2018). "In addition to proliferation and apoptosis, we next evaluated the influence of linc00511 on tumour cell metastasis." (PMID 28984028, 2018). "Linc00511 knockdown significantly delayed tumor growth in vivo." (PMID 30042171, 2018). "Our research showed that linc00511 promotes tumour angiogenesis in PDAC." (PMID 28984028, 2018). "To investigate whether linc00511 has a role in the pathogenesis of PDAC, we evaluated the consequences of linc00511 knockdown on tumour cell physiology by evaluating cell proliferation, apoptosis and invasive behaviour." (PMID 28984028, 2018). "Linc00511 was up‐regulated in most PDAC tissues compared with the adjacent non‐tumour tissues." (PMID 28984028, 2018). "Hence, LINC00511 has the ability to regulate the existence and activity of tumor stem cells." (PMID 39206156, 2024).
tumor (continued). "LINC00511 could also inhibit cell apoptosis and promote cell proliferation in some in vivo experiments where it was found that knocking down LINC00511 could inhibit tumor growth." (PMID 39206156, 2024). "This suggests that LINC00511 may be a tumor-promoting factor in LUAD." (PMID 35399076, 2022). "Also, LINC00511 induces the release of exosomes and promotes tumour progression." (PMID 34907642, 2022). "Additionally, LINC00511 knockdown restricted ccRCC cell proliferation, colony formation, and metastasis in vitro; accelerated cell cycle arrest at G0–G1 and apoptosis in vitro; and decreased tumor growth in vivo." (PMID 31434797, 2019). "The LINC00511-Enr and FIRRE-Enr clusters were more enriched in leukocyte movement and migration, while the cell proliferation and survival of tumor cells were similar for the LINC00511-Enr, FIRRE-Enr, and LINC00393-Enr clusters." (PMID 35893227, 2022). "According to these observations, LINC00511‐induced invadopodia formation supports ECM degradation and tumour invasion." (PMID 34907642, 2022). "The results verified that knockdown of Linc00511 inhibited tumor growth and metastasis in nude mice, while COL1A1 overexpression partially counteracted the tumor suppression mediated by Linc00511 silencing." (PMID 35842617, 2022). "All these data indicated that LINC00511 promoted GC cell migration, EMT and stemness in vitro and facilitated GC tumour growth in vivo." (PMID 34427967, 2021). "According to previous studies, LINC00511 can target miR‐625‐5/NFIX axis and promote the proliferation of tumours." (PMID 34427967, 2021). "According to the intersection of up-regulated lncRNAs in GSE18842 and GSE19188, seven lncRNAs (LINC00511, LINC01133, DUXAP10, LINC01296, BBOX1-AS1, AFAP1-AS1 and LINC01116) were found to be highly expressed in NSCLC tumor tissues in both datasets." (PMID 33931086, 2021). "However, it is interesting to note that the most PM-specific SFPQ-lncRNA interactors included genes associated with tumour suppressor function, such as EMX2OS and FENDRR, whereas the most A2058-specific SFPQ-lncRNA interactors comprise genes widely reported as oncogenic, such as LINC00511." (PMID 34218270, 2021). "The identified upregulated promoters of cancer progression included NR2F1-AS1 and LINC00511 in clPTC and CRNDE in ATC; downregulated tumour suppressors SLC26A4-AS1 in clPTC and RMST in ATC." (PMID 34408227, 2021). "Thanks to the relationship between LINC00511 and tumor size, we did the colony formation assay and CCK-8 assay to prove if knockdown of LINC00511 restrains cellular proliferation." (PMID 31897240, 2020). "Transfection-induced overexpression of LINC00511 and MAEL, as well as downregulation, highlighted the features of tumor cells, and LINC00511 overexpression reduced apoptosis in vitro." (PMID 31386627, 2019). "This discovery not only provides new insights into the molecular mechanisms of CCA but also suggests potential targets for the development of innovative treatment strategies, such as drugs targeting LINC00511, YTHDF2, or SOX2 to disrupt this loop and curb tumor progression." (PMID 39445001, 2024). "In particular, our results revealed that linc00511 may function as a ceRNA to mediate the expression of VEGFA through competition for hsa‐miR‐29b‐3p, hence serving as a tumour promoter in PDAC pathogenesis." (PMID 28984028, 2018). "Dysregulation of LINC00511 in different cancers (TNTP: tumor and non-tumor pairs of tissues)." (PMID 37124625, 2023). "However, whether the interaction of miR-15a-3p and linc00511 could regulate the expression of Bcl-xl downstream and the EMT process and further impact on tumor progression need our future explore." (PMID 30042171, 2018). "The high LINC00511 expression group was more positively correlated with larger tumour size (P = .026), wild‐type IDH1/2 (P = .043), recurrence (P = .011) and poor prognosis than the low LINC00511 expression group, however, not with other features such as gender (P = .157) and age (P = .7)." (PMID 31856394, 2020).
cancer (64 papers, 2014 to 2025). A tumor composed of atypical neoplastic, often pleomorphic cells that invade other tissues. "LINC00511 was downregulated in a variety of tumors, and this was linked to survival and metastasis in human cancers." (PMID 35790898, 2022). "More importantly, upregulated LINC00511 has been associated with prognosis, suggesting that it can represent a biomarker for prognosis in cancer patients." (PMID 32698787, 2020). "Additionally, a meta-analysis has revealed that increased LINC00511 expression level was associated with poor OS rates in multiple cancer types, suggesting its potential as an independent predictor for poor prognosis." (PMID 37434634, 2023). "The results showed that patients in the low expression group of LINC00511 had significantly better OS compared to those in the high expression group, further confirming the association between a low expression of LINC00511 and improved prognosis in cancer patients." (PMID 40076759, 2025). "With respect to LINC00511, studies have shown that its intracellular localization varies in different cancers." (PMID 39206156, 2024). "The current narrative review summarizes the role of LINC00511 in different cancers with an especial focus on its prognostic impact in human cancers." (PMID 37124625, 2023). "Molecular axes being regulated by LINC00511 in more than one type of cancer represent better targets for design of anti-cancer therapies since they can be applied in a wider range of malignancies." (PMID 37124625, 2023). "Over-expression of LINC00511 has been reported in a variety of cancers including colorectal, pancreatic, liver, thyroid and other types of cancers." (PMID 37124625, 2023). "Several studies have reported dysregulation (mainly upregulation) of LINC00511 in different cancers." (PMID 37124625, 2023). "Dysregulation of LINC00511 affects cancer pathogenesis through increasing cell proliferation and inhibiting cell apoptosis." (PMID 37124625, 2023). "First of all, the up-regulation of LINC00511 expression in CC samples was observed through the analysis of Gene Expression Profiling Interactive Analysis (GEPIA) database (gepia.cancer-pku.cn)." (PMID 36103025, 2022). "LINC00511 is a poor prognostic factor in cancer since its increased expression is crucial to malignant tumorigenesis." (PMID 36287120, 2022). "Anyhow, the actions of LINC00511 in impelling the malignant development of other cancers are echoed with those in CC." (PMID 35477702, 2022). "The link among LINC00511 expression profiles and cancer metastasis was measured by using a pooled odds ratio (OR) with a 95% confidence interval." (PMID 35790898, 2022). "LINC00511 has been widely confirmed to be an oncogene, is abnormally expressed in many tumors and induces the malignant biological behaviour of cancer cells." (PMID 34088337, 2021). "This is a novel mechanism by which LINC00511 regulates invadopodia biogenesis and exosome secretion to further promote cancer progression." (PMID 34088337, 2021). "Given the pronounced effect of LINC00511 knockdown in A2058 cells on cancer cell phenotype, we decided to investigate this gene further." (PMID 34218270, 2021). "LncRNAs can exert critical functions in the progression of various cancers, and LINC00511 has been proved to be important participant in many cancers, including GC,14, 24 in which LINC00511 was verified to be an oncogene." (PMID 34427967, 2021). "The relationship between LINC00511 expression and cancer progression was investigated by combining progression-free survival (PFS) studies." (PMID 32698787, 2020). "Several in vitro studies had demonstrated the functions of LINC00511 in cancer, but most of them focused on the ceRNA mechanism." (PMID 32382578, 2020). "In the present study, a first-time, comprehensive meta-analysis on the prognostic value of LINC00511 in diverse human cancers is presented." (PMID 32698787, 2020).
cancer (continued). "Long intergenic non-coding RNA 00511 (LINC00511) is highly expressed in diverse cancers and has a correlation with poor clinical outcomes for cancer patients." (PMID 32698787, 2020). "Regarding to HCP5 and LINC00511, a variety of studies have also suggested that they act as two crucial oncogenes in human cancers." (PMID 31061236, 2019). "LINC00511 exerts oncogenic effects on cell proliferation, cell-cycle, cell apoptosis, migration, invasion, and stemness in human cancers." (PMID 31434692, 2019). "To date, little is known about its involvement in PDAC, and the biological roles of linc00511 in cancer cells also remain elusive." (PMID 28984028, 2018). "Here, the knockdown of linc00511 induced cell cycle arrest at G1 phase and reduced the percentage of cancer cells in the S phase through the flow cytometry analysis and EdU assay." (PMID 30042171, 2018). "BIU87, T24 and 5637 cancer cells showed the higher expression of linc00511 than that of SV-HUC-1 cells." (PMID 30042171, 2018). "Our results indicated that high LINC00511 expression in cancer may come from the abnormal methylations of its promoter regions." (PMID 40076759, 2025). "Furthermore, the abnormal expression of LINC00511 has been observed in several other types of cancer besides STAD." (PMID 40076759, 2025). "Furthermore, we discovered that high expression of LINC00511 correlated with adverse clinical characteristics and a poor survival prognosis, underscoring the significant role of LINC00511 in cancer onset and progression." (PMID 39445001, 2024). "LINC00511 is known to be dysregulated in various human malignant tumors." (PMID 39206156, 2024). "Therefore, LINC00511-modifying modalities can be used as possible strategies for defeating cancer metastasis." (PMID 37124625, 2023). "Moreover, LINC00511 can promote progression of this type of cancer through binding to EZH2 and LSD1 and decreasing expression levels of LATS2 and KLF2." (PMID 37124625, 2023). "Herein, we performed a comprehensive literature and in silico databases search listing lncRNAs, lincRNAs including LINC00511, lncRNAs’ SNPs, as well as LINC00511 SNPs in different cancer types, focusing on their role in various cancer types and mechanism(s) of action." (PMID 37888204, 2023). "Moreover, LINC00511 can induce BC oncogenesis through sponging miR-150, miR-185, miR-185-3p, and miR-29, in addition to other discussed types of cancer that can be induced by LINC00511." (PMID 37888204, 2023). "Specifically, LINC00511 has a crucial role in various types of cancer." (PMID 37888204, 2023). "LINC00511 has been identified as a lncRNA overexpressed in various cancers." (PMID 35399076, 2022). "Numerous studies have revealed that LINC00511 is a multipotent cancer promoter." (PMID 35399076, 2022). "LINC00511 presents multiple oncogenic functions, including the promotion of cellular proliferation, acceleration of metastasis, and influence on the invasive behavior of cancer cells." (PMID 36287120, 2022). "The processes behind LINC00511's oncogenic functions were complicated, which may assist to clarify how LINC00511 expression levels in cancers were clinically significant." (PMID 35790898, 2022). "Except for CC, the promoting actions of LINC00511 have been reflected in other cancers." (PMID 35477702, 2022). "LINC00511 functions as a molecular sponge in several types of cancers." (PMID 36103025, 2022). "Especially, FOXC1 and LINC00511 were expressed at a higher level in ER− cancers." (PMID 34783649, 2021). "Taken together, these findings suggested that LINC00511 might serve as a biomarker for prognosis and metastasis in malignant tumors." (PMID 32713253, 2020). "Numerous studies have identified that LINC00511 promoted the incidence of various cancers." (PMID 32242897, 2020). "LINC00511 can thus serve as prognostic biomarker for cancer patients." (PMID 32698787, 2020). "Noteworthily, overexpression of LINC00511 was shown to be a predictor for cancer prognosis." (PMID 32698787, 2020).
cancer (continued). "Additionally, we also made a comprehensive review of the biological functions of LINC00511 in malignant tumors and the relevant mechanisms." (PMID 32713253, 2020). "LINC00511 has been demonstrated to be a poor predictor for both cancer recurrence and progression." (PMID 32698787, 2020). "This study aimed to evaluate the prognostic profile of LINC00511 in cancer patients." (PMID 32733536, 2020). "Further investigation of LINC00511 in oncogenesis and cancer progression is necessary." (PMID 31395854, 2019). "LINC00511 is dysregulated in multiple types of human cancer." (PMID 31434797, 2019). "Generally, LINC00511 expression was overexpressed in most types of human cancers, but more studies are necessary to explore the clinical significance of LINC00511 expression in various kinds of cancer." (PMID 31434692, 2019). "Therefore, further research on the regulatory mechanisms of LINC00511 dysregulation in BC would be beneficial for revealing the molecular nature this cancer and this exercise may point to potential new therapeutic targets to combat this disease." (PMID 39206156, 2024). "Therefore, LINC00511 is a potential cancer biomarker and a promising therapeutic target." (PMID 39206156, 2024). "Moreover, LINC00511 had been shown in previous studies to promote cancer through various mechanisms, such as competitively binding with microRNAs to downstream oncogenic mRNAs, activating multiple oncogenic signaling pathways, and recruiting proteins to regulate downstream gene expression." (PMID 39445001, 2024). "Since it has been repeatedly reported that LINC00511 principally affects cancer progression by serving as a competing endogenous RNA (ceRNA) via the lncRNA/microRNA (miR)/mRNA axis, we hypothesize that LINC00511 could also mediate OA severity through the ceRNA network." (PMID 38934781, 2024). "Moreover, LINC00511 exhibits cancer-promoting effects in multiple types of cancers." (PMID 36103025, 2022). "As previously reported, we conducted the meta-analysis of these studies and found that high LINC00511 expression may serve as an independent predictor for poor overall survival prognosis in cancers (HR = 3.37; 95% CI: 1.96–5.79; p < 0.001; I2 = 82.5%; PH = 0.001)." (PMID 32698787, 2020). "Based on our findings, LINC00511 may serve as a novel prognostic biomarker for cancer patients." (PMID 32698787, 2020). "Others, such as LINC01220, CYTOR, LINC00910, LINC00511, PURPL, and MZF1-AS1, have been described so far only in cancer." (PMID 38616192, 2024). "Our findings highlight the significance of the LINC00511–YTHDF2–SOX2 regulatory network in driving CCA progression and maintaining cancer stemness." (PMID 39445001, 2024). "LncRNAs, such as HOTAIR, H19, LncTCF7, LUCAT1, MALAT1, LINC00511, and FMR1-AS1, have been described as key regulators of stemness in cancer, allowing cancer cells to acquire this phenotype." (PMID 35954194, 2022). "However, the clinical importance of LINC00511 overexpression in human cancers was still under debate, therefore, we used The Cancer Genome Atlas (TCGA) data to conduct a meta-analysis and bioinformatics research to analyze the clinical significance of LINC00511 expression level comprehensively." (PMID 35790898, 2022). "The validation results were highly in great agreement with those in microarray, and the expression tendency of HOTAIR, TINCR, LINC00511, LINC00520, MEG3, and ZNF667-AS1 was also consistent with literature reports in other carcinomas." (PMID 31196171, 2019). "It has been shown that various lncRNAs, such as LINC00511 or XIST, served as a modular scaffold of EZH2/PRC2 complexes and interacted and coordinated their localization, thereby contributing to cancer progression." (PMID 29228709, 2017). "Moreover, LINC00511 was found to interact with a variety of signaling pathways including JAK2/STAT3, Wnt/β-catenin, and PTEN/AKT/FOXO1, in the pathogenesis of cancers." (PMID 32698787, 2020).